BCAR3 (BCAR3 adaptor protein, NSP family member)
Diseases named in the same sentence as BCAR3 in open-access papers (continued):
Sharing a sentence is not in itself a finding about the gene and the disease.
cataract (1 paper, 2018). Partial or complete opacity of the crystalline lens of one or both eyes that decreases visual acuity and eventually results in blindness. "Studies have shown that the BCAR3 gene is the first spontaneous mutation associated with cataracts caused by lens compression." (PMID 30563570, 2018).
fungal infection (1 paper, 2017). "A study using human polymorphonuclear leukocyte (PMNs) showed that BCAR3 was down-regulated by gliotoxin, a mycotoxin produced by A. fumigatus, which further enhances the importance of this gene in the host immune response during fungal infection." (PMID 28797245, 2017).
gastric cancer (1 paper, 2022). A primary or metastatic malignant neoplasm involving the stomach. "We obtained 43 DEGs with the adjusted p < 0.05 and | log2 FC)|>1, of which JUNB, ID1, CDKN1C, ID3, and BCAR3 were lowly expressed in gastric cancer tissues, and the remaining DEGs were highly expressed in gastric cancer tissues." (PMID 36467074, 2022).
glioblastoma (1 paper, 2015). The most malignant astrocytic tumor (WHO grade IV). "A gene that resulted strongly underexpressed in our STC samples vs the LTC ones was BCAR3, whose role in glioblastoma has never been revealed before." (PMID 26188123, 2015).
lymph node metastasis (1 paper, 2014). "Moreover, we also found that patients with lymph node metastasis tend to carry loss of heterozygosity at BCAR3 alleles, indicating that BCAR3 likely plays a role in preventing disease progression." (PMID 25499443, 2014).
medullary thyroid carcinoma (1 paper, 2026). "Furthermore, BCAR3 methylation showed differential patterns across TC subtypes, with medullary thyroid carcinoma exhibiting the lowest methylation levels." (PMID 41595187, 2026).
Merkel cell carcinoma (1 paper, 2023). "While the observed integration sites in this study are unique and have not been observed in Merkel cell carcinoma, HPV16 integration has been reported previously in BCAR3." (PMID 36961501, 2023).
mood disorder (1 paper, 2024). A cognitive disorder a disturbance in which the person's mood is hypothesized to be the main underlying feature. "Further, genes linked to mood disorders and stress response were identified (BCAR3, FAM214A, MAML3)." (PMID 39055655, 2024).
oral cancer (1 paper, 2021). "We first explored BCAR3 expression in SCC25, FaDu, HaCaT, and normal adjacent tissue obtained during oral cancer surgeries." (PMID 34707118, 2021).
serous ovarian cancer (1 paper, 2025). "5′-tRF-Glu-CTC inhibits cell proliferation in high-grade serous ovarian cancer (HGSOC) by targeting the BCAR3 3′-UTR." (PMID 40295511, 2025).
triple-negative breast carcinoma (1 paper, 2013). An invasive breast carcinoma which is negative for expression of estrogen receptor (ER), progesterone receptor (PR), and human epidermal growth factor receptor 2 (HER2). "BCAR3 protein expression is elevated in cell lines representative of triple-negative breast cancers compared to estrogen receptor-positive cells." (PMID 23762409, 2013). "Since BCAR3 has been shown to function through Cas to activate c-Src, we suggest that its upregulation in triple negative breast cancer cells may contribute to the elevated c-Src activity seen in these tumors." (PMID 23762409, 2013).
cancer (16 papers, 2012 to 2026). A tumor composed of atypical neoplastic, often pleomorphic cells that invade other tissues. "In the realm of oncology, the development of inhibitors targeting the BCAR3 gene presents a promising therapeutic avenue, particularly given BCAR3’s implicated role in cancer cell migration, survival, and proliferation." (PMID 38730626, 2024). "In the present study, we found that BCAR3 expression is significantly associated with poor clinical outcomes of HNSCC cancer patients." (PMID 34707118, 2021). "In addition, it was found that BCAR3 expression was associated with perineural invasion, an important process of cancer dissemination." (PMID 34707118, 2021). "These functions underscore BCAR3’s pivotal role in cellular behavior regulation and highlight its potential as a therapeutic target in cancer treatment." (PMID 38730626, 2024). "Specifically, BCAR3’s involvement in cell movement aids the metastatic spread of cancer, allowing cells to invade new tissues." (PMID 38730626, 2024). "These interactions not only affect tumor growth and progression but also modulate the efficacy of immunotherapeutic strategies, placing BCAR3 at a critical intersection of cancer growth regulation and immune response modulation." (PMID 38730626, 2024). "The discussion covers BCAR3’s involvement in integrin signaling and its impact on cancer cell migration, its capability to induce anti-estrogen resistance, and its significant functions in cell cycle regulation." (PMID 38730626, 2024). "The role of BCAR3 in immune cells related to cancer is a critical area of research with potential implications for therapeutic strategies." (PMID 38730626, 2024). "This divergence emphasizes the importance of context-specific understanding of BCAR3’s function in cancer biology, suggesting that BCAR3’s role is highly dependent on the molecular and cellular environment of the tumor." (PMID 38730626, 2024). "This involves testing the candidate compounds in various cancer cell lines and animal models to evaluate their efficacy in inhibiting BCAR3-mediated pathways." (PMID 38730626, 2024). "Overall, the development of BCAR3 inhibitors is still at a nascent stage, and extensive research is needed to translate these early-stage discoveries into viable cancer therapies." (PMID 38730626, 2024). "Stiff 3D culture wasassociated with the downregulation of tumor suppressors (LATS1, BCAR3, CDKN2C), as well as theupregulation of cancer-associated genes (RAC3)." (PMID 38466617, 2024). "This highlights the importance of further research into BCAR3’s functions and interactions within the immune system to develop effective cancer immunotherapies." (PMID 38730626, 2024). "BCAR3 has become a focal point in the study of cancer biology due to its complex role in modulating cell signaling pathways that influence cancer progression and response to therapy." (PMID 38730626, 2024). "Isoform-specific expression profiling through RNA sequencing (RNA-seq) is a critical research approach for understanding the diverse roles of BCAR3 mRNA isoforms in various cancer subtypes." (PMID 38730626, 2024). "Further highlighted is BCAR3’s modulation of immune responses within the tumor microenvironment, a novel area of interest that holds potential for innovative cancer therapies." (PMID 38730626, 2024). "This intricate interaction beckons further investigation to decode the pathways through which IL-1 and TNF affect BCAR3 gene activity, particularly focusing on its implications in cancer biology." (PMID 38730626, 2024). "This expression pattern, coupled with the colocalization of BCAR3 and its binding partner p130Cas, suggests a pivotal role in facilitating cancer cell invasiveness." (PMID 38730626, 2024). "BCAR3 plays critical roles in several biological processes that are pivotal for cancer development, including cell motility, hormone resistance, and immune system interactions." (PMID 38730626, 2024).
cancer (continued). "This review comprehensively explores the gene BCAR3, detailing its regulation at the gene, mRNA, and protein structure levels, and delineating its multifunctional roles in cellular signaling within cancer contexts." (PMID 38730626, 2024). "In this review, we have explored the multifaceted roles of BCAR3 in cancer biology, emphasizing its regulation at the genetic, transcriptomic, and protein levels and its involvement in critical cellular processes." (PMID 38730626, 2024). "The exploration of BCAR3 not only helps in understanding the complex biology of cancer but also opens up new avenues for therapeutic intervention." (PMID 38730626, 2024). "Conclusively, BCAR3 emerges not only as a critical molecular player in cancer pathways but also as a promising target for innovative treatments." (PMID 38730626, 2024). "Research on BCAR3 mRNA expression across various cancer types highlights its complex role in tumor biology." (PMID 38730626, 2024). "By employing RNA-seq, researchers can generate a high-resolution map of BCAR3 isoform expression across a wide range of cancer cell lines and tumor samples." (PMID 38730626, 2024). "This review aims to dissect the multifaceted aspects of BCAR3, from its gene expression, mRNA regulation, and protein structure to its intricate functions within cells that contribute to cancer dynamics." (PMID 38730626, 2024). "Through comprehensive exploration and detailed analysis, this review aims to consolidate our understanding of BCAR3, proposing new research avenues and highlighting its potential as a key target in the fight against cancer." (PMID 38730626, 2024). "Despite the recognition of BCAR3’s role in cancer cell signaling and its potential in modulating therapy responses, research has yet to delve into its functions within the context of CSCs." (PMID 38730626, 2024). "At the cellular level, BCAR3 is integral to several signaling pathways, particularly those involving integrin signaling, which plays a crucial role in cancer cell migration and metastasis." (PMID 38730626, 2024). "These functions make BCAR3 an important player in the pathology of cancer, affecting how cancer cells grow, spread, and resist various treatments." (PMID 38730626, 2024). "Despite its known roles in cell adhesion and migration in cancer cells, the function of BCAR3 in immune cells remains poorly understood, highlighting a significant gap in the current research landscape." (PMID 38730626, 2024). "How BCAR3 and FMNLs are regulated and their functions in cancer remained unclear, and we observe that methylation of BCAR3 recruits FMNLs to increase lamellipodia fitness." (PMID 38296970, 2024). "Understanding the regulation of the BCAR3 gene in cancer is crucial, given its roles in modulating cell survival, proliferation, and migration." (PMID 38730626, 2024). "This discrepancy underscores the nuanced role BCAR3 plays in cancer progression and response to therapy, highlighting its dual nature." (PMID 38730626, 2024). "P21 activated kinase 4 (PAK4) and Breast cancer anti-estrogen resistance 3 (BCAR3) have been reported to be involved in numerous aspects in tumorous progression." (PMID 35842733, 2022). "Previous studies in cancer cells and fibroblasts found that BCAR3 localizes to integrin adhesions and that BCAR3 over-expression can increase Cas in membrane ruffles." (PMID 34169835, 2021). "In other cancer forms, BCAR3’s impact is equally significant but manifests differently." (PMID 38730626, 2024). "Gene expression analysis through quantitative PCR or RNA sequencing could determine the levels of BCAR3 in different immune cells from cancer patients." (PMID 38730626, 2024). "Exploiting BCAR3’s immunoregulatory capacity could intensify the therapeutic impact of cancer immunization and cellular therapies." (PMID 38730626, 2024).
cancer (continued). "Finally, detailed confocal adaptive optics microscopy analyses of cancer cells migrating from the spheroid mass showed that cells impaired for BCAR3 methylation presented protrusions defects." (PMID 38296970, 2024). "Targeting BCAR3 to prevent or reverse the polarization of macrophages towards a tumor-promoting M2 phenotype could pave the way for novel cancer treatments that harness the body’s immune system." (PMID 38730626, 2024). "This research approach could provide significant insights into how these transcription factors regulate BCAR3, potentially elucidating new mechanisms of cancer progression and identifying targets for therapeutic intervention." (PMID 38730626, 2024). "Furthermore, BCAR3’s involvement in regulating the cell cycle and its interactions within the immune system illustrate its broader implications in cancer therapy." (PMID 38730626, 2024). "In summary, the dynamic interactions of BCAR3 with BCAR1, HEF1, and various GTPases provide a complex regulatory network that is essential for normal cell cycle progression and potentially implicated in cancer when dysregulated." (PMID 38730626, 2024). "In summary, BCAR3 is a critical co-regulatory network that impacts lamellipodia dynamics and supports the development of membrane ruffles, crucial for cell migration and the invasion process in cancer." (PMID 38730626, 2024). "Moreover, isoform-specific expression profiling can aid in understanding the molecular mechanisms of BCAR3 action in cancer cells." (PMID 38730626, 2024). "BCAR3 is required for the migration of cancer cells and fibroblasts in single-cell assays but its importance in single and collective epithelial cell migration is unknown." (PMID 34169835, 2021). "We hypothesize that BCAR3 may function more in promoting the interaction between cancer cells and nerve cells to promote perineural invasion rather than simply promoting cell migration." (PMID 34707118, 2021). "Additionally, exploring BCAR3′s role within the immune context of the tumor microenvironment could unlock new therapeutic paradigms, potentially transforming cancer treatment by leveraging the body’s own immune system against tumor cells." (PMID 38730626, 2024). "By deepening the understanding of BCAR3’s role in immune cells, researchers can unlock new avenues for cancer therapy that manipulate BCAR3-mediated pathways to boost the immune attack on tumors or counteract the immune evasion strategies employed by cancer cells." (PMID 38730626, 2024). "Notably, Junjie Hou and colleagues have provided significant insights into how miR-199a/b-3p curtails the spread and growth of colorectal cancer by targeting the 3′-untranslated region (3′-UTR) of BCAR3 mRNA, thereby disrupting cancer cell proliferation, migration, and invasion." (PMID 38730626, 2024). "This synthesis of BCAR3′s roles across different cellular and molecular contexts hopes to spur further investigation and innovative treatments that could significantly impact cancer therapy." (PMID 38730626, 2024). "However, our data suggests that the methylation of BCAR3 induced by SMYD2 overexpression highjacks the BCAR3-p130Cas regulatory mechanism of cell adhesion and cell protrusion by directly recruiting major actors of lamellipodia maturation, enhancing cancer cells capacity." (PMID 38296970, 2024). "Thus far, studies concerning BCAR3 in other types of cancer remain scarce and the role of BCAR3 in HNSCC is currently unknown." (PMID 34707118, 2021). "On the other hand, “hub genes” of four other modules contain POU2F3 (↑), CENPH (↑), PCSK6 (↑) and HERC2 (↑), BCAR3 (↑), DOHH (↑), NLK (↑), SCN2A (↑), CACNA2D3 (↓) and CTNND2 (↓), which were commonly reported related to cancer." (PMID 27602771, 2016). "Interestingly, complementation with WT, but not BCAR3 harboring a K334A substitution, could fully restore MDA-MB-231 cancer cell migration velocity." (PMID 38296970, 2024).
tumor (16 papers, 2013 to 2026). "The upregulation of BCAR3 in M2 macrophages, which are associated with tumor progression, underscores the potential of BCAR3 as a target for therapeutic intervention." (PMID 38730626, 2024). "Specifically, in triple-negative breast cancer (TNBC), higher levels of BCAR3 mRNA are associated with decreased survival rates, underscoring its contribution to tumor aggressiveness and poor prognosis." (PMID 38730626, 2024). "Altogether, these results indicate that loss of BCAR3 expression correlates with an invasive tumor phenotype with increased lymph node involvement." (PMID 25499443, 2014). "This suggests that a severe loss of BCAR3 expression correlates with markedly increased chance of tumor relapse." (PMID 25499443, 2014). "The interaction of BCAR3 with macrophage polarization presents a critical insight into its role within the tumor microenvironment." (PMID 38730626, 2024). "While elevated BCAR3 levels in TNBC and HNSCC are associated with increased tumor aggressiveness and poorer outcomes, its diminished expression in Luminal A and B subtypes correlates with resistance to endocrine therapy and worse prognosis." (PMID 38730626, 2024). "Subsequently, statistical analysis helps correlate the presence and levels of specific BCAR3 isoforms with various clinical parameters, such as patient survival rates, tumor grade, response to treatment, and recurrence rates." (PMID 38730626, 2024). "Research into how BCAR3 expression is controlled within the tumor microenvironment, where inflammatory cytokines such as IL-1 and TNF are prevalent, is particularly vital." (PMID 38730626, 2024). "IL-1 and TNF, often elevated in the tumor milieu, play significant roles in inflammatory processes and have been shown to engage specific transcription factors that bind to the BCAR3 promoter region." (PMID 38730626, 2024). "There is a compelling need to investigate the expression and functionality of BCAR3 in immune cells within the tumor microenvironment." (PMID 38730626, 2024). "In particular, a tumor-suppressive role has been documented for 5′-tRF-GluCTC, which inhibits cell proliferation by directly targeting BCAR3 3′-UTR." (PMID 35008188, 2021). "BCAR3 silencing significantly attenuated the proliferation of HNSCC cells, whereas BCAR3 depletion inhibited tumor growth in vitro." (PMID 34707118, 2021). "In contrast, BCAR3 and cas interact to activate Rac1, rapidly breaking down adhesion and resulting tumor invasion." (PMID 30563570, 2018). "The BCAR3 signaling pathway would then be in place to promote rapid and efficient invasion/migration of these tumor cells to distal sites in response to these environmental stresses." (PMID 23762409, 2013). "Notably, BCAR3 hypomethylation was more pronounced in cases with larger tumor size and advanced disease stage." (PMID 41595187, 2026). "Similarly, overexpression of BCAR3 was also found in tumor tissues based on data from another cohort from the GEO database (GSE31056)." (PMID 34707118, 2021). "When BCAR3 is low expressed, ER is highly expressed and inhibits tumor progression." (PMID 30563570, 2018). "The expression of BCAR3 might influence key immune processes such as the migration of immune cells into the tumor, their survival within the immunosuppressive tumor milieu, and their ability to execute an effective anti-tumor response." (PMID 38730626, 2024). "Additionally, immunohistochemical staining in tumor sections could visualize BCAR3 expression relative to immune cell markers, providing insights into its spatial and functional relevance in the tumor microenvironment." (PMID 38730626, 2024). "Indeed, combined loss and deletion of BCAR3 alleles increased from 18% in N0 tumors (no lymph node invasion), to 31% in N1 tumors (tumor cells in regional lymph nodes) and to 50% in N2 tumors (tumor cells in regional and distant lymph nodes)." (PMID 25499443, 2014). "Indeed, low BCAR3 levels in tumor cells may lead to potent responses to TGFβ." (PMID 25499443, 2014).